CD27 (CD27 molecule)
Diseases named in the same sentence as CD27 in open-access papers (continued):
Sharing a sentence is not in itself a finding about the gene and the disease.
tumor (continued). "CD27, which belongs to TNFR superfamily, can enhance CAR-T cell expansion, effector functions, and survival in vitro, as well as augmenting CAR-T cell persistence and anti-tumor activity in vivo." (PMID 41293181, 2025). "The significantly lower expression of CD27 and CD127 by tumor-infiltrated T cells in our cohort might emphasize their effector memory state." (PMID 41221283, 2025). "In contrast with CD70, it is shown that high CD27 expression was associated with decreased CD45 + and CD8 + cellular densities, but only in the stroma compartment, not in tumor nests." (PMID 40205178, 2025). "High CD27 mRNA correlated with poor LUAD but improved LUSC prognosis, while elevated CD27 protein in paired LUAD/LUSC tissues showed no prognostic significance from Clinical Proteomic Tumor Analysis Consortium (CPTAC) datasets." (PMID 41377765, 2025). "Multivariate analysis confirmed that CD70 expression and tumor stage were significant prognostic factors for OS, while CD27 was not." (PMID 40205178, 2025). "CD27 showed coexpression with scattered vimentin + CAFs (arrow) and CD3 + T-cells (arrows) in the stroma, and with a moderate number of CD68 + TAMs in the stroma compartment and inside tumor nests (arrows)." (PMID 40205178, 2025). "Additionally, CD27 co-stimulation should support human CAR T-cell persistence and anti-tumor activity in vivo." (PMID 39594628, 2024). "CD27, when it binds to its native ligand CD70, can promote T cell proliferation and differentiation into effector and memory T cells, which have potent anti-tumor potential." (PMID 38601154, 2024). "Moreover, qRT-PCR results revealed significant upregulation of CD27, CXCL13, IFNG and GZMB in tumor-specific T cells using." (PMID 39033098, 2024). "Blocking CD27 signaling in combination with anti-PD-1 therapy has been shown to increase the number of CD8+ T cells within tumors and improve the CD8+ T cell/Treg ratio, thereby enhancing the anti-tumor efficacy." (PMID 38500876, 2024). "As a T cell co-receptor that has not been fully studied, CD27 has a great possibility to play a regulatory and therapeutic role in tumor progression." (PMID 38169519, 2024). "In cKO mice, the senescence inhibition markers CD27 and CD28 were induced in tumor-infiltrating CD8+ T cells, whereas the level of the metabolism-associated senescent cell marker β-gal was reduced, suggesting that knockout of Cbx4 enhances the anti-senescence capacity of T cells." (PMID 38994031, 2024). "This interaction activates the CD27/CD70 signalling pathway, promoting effector and memory T‐cell differentiation in CD8+ T cells, thereby enhancing their functionality and active participation in the immune response against tumours." (PMID 39031800, 2024). "Quantification of circulating lymphocyte populations in the peripheral blood of NF1 patients using flow cytometry revealed increased effector CD8+/CD27- and activated CD8+/CD57+ T-cell populations in subjects with low PNF and CNF tumor burden compared to patients with high tumor burden." (PMID 38473354, 2024). "Moreover, the expression of ADAM10 was reciprocally exclusive with some tumor immune checkpoint genes, such as VEGFB, LAG3, IL4, TNFRSF18, TNFRSF4, TNF receptor superfamily member 14 (TNFRSF14), CD27, CCL5, etc.." (PMID 39211038, 2024). "Consistent with the regulon profile, tumor-reactive T cells exhibited higher expression of pro-inflammatory effector molecules such as IFNG, TNF, and PRF1 and lower expression of genes like LBT, CD27, and CD28." (PMID 39243082, 2024). "Notably, tumor-reactive CD8+ T cells - inclusive of cytotoxic, terminally exhausted, and pre-exhausted cells - present a higher proportion of CD27+ cells in comparison to all CD4+ T cells, Th17 cells, and naïve T cells." (PMID 37545491, 2023).
tumor (continued). "We have obtained a predictive model for TNM which combines peripheral blood parameters (% CD27+ CD4+ lymphocytes, % IDO+ monocytes, LAG3 MFI in CD4+ lymphocytes) with histological grade and tumor size and discriminates pTa and pT1 tumors with a sensitivity of 75% and specificity of 96.65%." (PMID 36900156, 2023). "We therefore evaluated the baseline expression levels of CD27 and CD20 in tumor tissues by mIF." (PMID 37005910, 2023). "Interestingly, when a CD27 intercellular domain was incorporated, the antitumor activity of T2-CAR T cells was enhanced, especially in tumor-bearing mouse models." (PMID 37954074, 2023). "These CD27-based T2-CAR T cells demonstrated a higher survival rate in the spleens and tumor tissues of tumor-bearing mice and exhibited upregulated IL-7Rα expression and downregulated PD-1 expression, indicating a multifaceted mechanism of enhanced killing effect." (PMID 37954074, 2023). "Both series yielded unique opportunities to investigate the prognostic value of the CD27−:CD27+ ratio as a surrogate of clonal T cell expansions in patients treated with regimens including lenalidomide, an IMID that requires tumor-reactive T cells to mediate its anti-MM effect." (PMID 37730678, 2023). "On the other hand, tumor cell segments displayed lower levels of CD44, CD40, and CD27." (PMID 38044986, 2023). "Anticipating that the tumor environment in CLL patients may affect SIGLEC10 expression, we also included normal naïve CD5− B cells, naïve CD5+ B cells, and CD27+ memory B cells from 5 age‐matched healthy donors." (PMID 37424400, 2023). "We found that CD70-KO in C666 cells greatly enhanced cytotoxicity-dependent tumor cell death, preferentially in a co-culture system similar to the physiological T-cell landscape in NPC patients, with a higher expression of CD27 on CD4+ T cells." (PMID 37024479, 2023). "When tumor cells overexpress CD70, CD27 expression in tumor-infiltrating Tregs may facilitate immune evasion." (PMID 37849799, 2023). "CD27 is involved in CD8+ T cell activation and memory formation that augments anti-tumor activity." (PMID 36707896, 2023). "Considering the substantial co-expression of CD27 and CD26, a considerable decline in the proportion of CD26+CD8+ T cells may deprive CLL patients of the potent anti-tumor activity of this T cell subset." (PMID 36707896, 2023). "Preliminary in vitro analysis has indicated that blocking CD70 or CD27 can mitigate Raji-specific T-cell activation, however, in vivo data with CD70 KO Raji cells indicated that T-cell-mediated tumor control is not solely dependent on the CD70-CD27 axis." (PMID 37087494, 2023). "Within the seven-gene panel, CD27 is an emerging target for cancer immunotherapy involved in PD1 and CD70 blockades, CD8+ T cell expansion, and anti-viral/anti-tumor T cell immunity." (PMID 36551208, 2022). "Interaction of the MHC/tumour antigen epitope complex with the T‐cell receptor and costimulatory signals (including CD70/CD27) may lead to the activation of CD4+ and CD8+ T cells." (PMID 36471481, 2022). "CD27/CD70 interaction normally boosts T cell activation, differentiation, and promotes the clonal expansion of effector T cells, features for which CD27 targeting is being exploited in antibody-mediated anti-tumor strategies." (PMID 35053463, 2022). "Although we observe a trend of decreased CD27 expression in MM compared to SMM, it raises the question of the extent to which previous results were confounded by increasing tumor purity as the disease progresses." (PMID 36396631, 2022). "In other words, CD27, EDA, TNF, TNFRSF12A, TNFRSF13C, and TNFRSF9 expression may also affect the immunotherapy effect on tumours by regulating the expression of immune checkpoint molecules in the tumour microenvironment." (PMID 35392242, 2022).
tumor (continued). "We previously demonstrated that stimulation of the TNFRSF member, CD27 on T cells, promotes activation of bystander myeloid cells leading to increased antibody-dependent cellular phagocytosis (ADCP), in the context of a second tumour-targeting mAb16." (PMID 35288635, 2022). "Finally, a PD‐1–CD70 fusion protein has recently been described that can target tumour cells by blocking the PD‐1–PDL1 interaction and provide the missing CD70 activation signal to CD27+ T cells." (PMID 36471481, 2022). "The CD27-positive, CD38-positive, and PAX5-negative tumor-induced plasmablast-like-enriched B cell (TIPB) population regulates T cell-recruiting chemokines (CCL3, CCL4, and CCL5) and increases the number of tumor-infiltrating T cells." (PMID 36361781, 2022). "Additionally, we injected DT in combination with anti-PD-1 antibody to assess synergistic effects of Treg-derived CD27 with concomitant blockade of the PD-1 signaling pathway on CD8+ T cell numbers and effector functions within the tumor." (PMID 34423375, 2022). "Interestingly, even though eliciting the strongest anti-tumor response, the DAP-10/CD27 G3 CAR-T cells tended to be present at lower frequencies compared to CD28 G2 CAR-T cells in vivo." (PMID 35053463, 2022). "In contrast to hematological malignancies, expression of CD27 on the tumor cells has never been reported in solid tumors." (PMID 34991665, 2022). "In a recent study, a library of CAR-T cell constructs with several co-stimulatory domains was evaluated, with the combination of CD27 and DAP-10 yielding the best anti-tumor response in vitro against 24JK erbB2-positive sarcoma cells as well as in vivo in NOD-SCID mice." (PMID 35053463, 2022). "sCD27 might interfere with the conjugation of membrane-bound CD27 and CD70, thereby affecting the priming of CD8+ T cells and subsequent anti-tumor immunity." (PMID 35874720, 2022). "However, a higher expression of CD27, TNFRSF13C, and TNFRSF9 and a lower expression of EDA in tumours indicated better prognosis." (PMID 35392242, 2022). "In oncology, CD70 is aberrantly expressed on malignant cells without (solid tumors) or with CD27 co-expression (hematological malignancies), facilitating immune evasion through the tumor microenvironment (TME) and tumor progression." (PMID 34991665, 2022). "Certain positive regulatory factors, such as CD27, CD28, CD30, ICOS, and negative regulatory factors, such as CTLA4, PD-1, BTLA, TIM3, andLAG3, at immune checkpoints affect the recognition and apoptotic ability of the immune system against tumour cells." (PMID 36118669, 2022). "In addition, PD-1 Ab treatment has been shown to lead to the expansion of a CD8 T-cell cluster in the tumor, expressing Tbet+Eomes+MHCII+BATF+PD-1+TIM-3+CD27+CD69+Gata-3+ that correlated with small tumor size." (PMID 34912335, 2021). "In multiple in vitro and murine tumor models, PD1/PDL1 blockade in combination with an agonist CD27 monoclonal antibody was shown to enhance CD8+ cytotoxic T-cell expansion and function in an IL-2 dependent manner with gene expression changes promoting T-cell proliferation." (PMID 34630390, 2021). "In summary, tumor-specific CD8+ T cells in patients with NSCLC demonstrate divergent differentiation fates toward Temra subset, largely with two distinct phenotypes based on the expression of CD27 and CD28 (CD27−CD28− DN and CD27+CD28+ DP)." (PMID 34593620, 2021). "We also found that B cell related proteins (CD20, BAD, BCL-2, CD27, BIM) were most highly expressed in the stromal compartments while expression of lymphocyte-related markers (CD3, CD8, CD4, Tim-3) were elevated in tumor compartments." (PMID 34838031, 2021). "Remarkably, circulating class‐switched memory B cells (CD27+IgD−) showed a strong inverse correlation with CD68 staining grade, while intermediate monocytes (CD14++CD16+) negatively correlated with CD3+ and CD5+ cell density in the tumor." (PMID 33024560, 2020).
tumor (continued). "Interestingly, a small subset of genes enriched in tumor Treg cells such as CTLA4, TIGIT, TNFRSF9, CD27, and LAYN are also highly expressed by exhausted tumor‐infiltrating CD8+ T cells reflecting a shared program of activation and exhaustion in these cells." (PMID 32272497, 2020). "Notably, some genes related to exhaustion were also overexpressed in tumor‐infiltrating Tregs including TYMS, KIAA0101, CXCL13, CD27, HLA‐DQB1, HLA‐DMA, ENTPD1, CD200, DUSP4, and ZBED2." (PMID 32659053, 2020). "Our unpublished work suggests that CD27− and CD27+ γδ T cells have different metabolic requirements, which might partially explain the enrichment of the IL‐17+ subset over the IFN‐γ+ one in the tumor, observed in a number of cancer models." (PMID 31624593, 2019). "Tumor-infiltrating memory B cells were characterized in both Blo and Bhi samples by the high expression of CD27, absent expression of IgD and low expression of IgM, indicating a classical memory, predominantly class-switched phenotype." (PMID 31623665, 2019). "Therefore, we analyzed the levels of expression of IL-2, IL-2RA and CD27 together with CD40LG and the anti-apoptotic regulator BCL2L1 on CD8+ TILs isolated from peripheral blood and tumor tissues of Bhi OPSCC patients (n = 4; Cohort 3)." (PMID 31623665, 2019). "However, a large fraction of the tumor-resident CD8+ T-cells have phenotypic changes, with high levels of programmed death-1 (PD-1) and Tim-3, and low levels of the immune co-receptors CD27 and CD28, losing their anti-tumor functions." (PMID 31181729, 2019). "In contrast, the neoantigen-specific T cells found within the non-responder group more often displayed a memory-like phenotype (CD27-high, CD28-high, and CD127-high) and may be less effective in carrying out an anti-tumor response." (PMID 31511069, 2019). "This may explain why neutrophil-derived ROS selectively impacted on CD27− γδ17 T-cell proliferation compared to CD27+ γδ T cells, CD8+ or CD4+ T cells in neutrophil-rich tumor models." (PMID 29750788, 2018). "TIB themselves can present antigens to promote anti-tumor immunity while, independent of the MHC pathway, engage CD27 on the surface of T cells to amplify anti-tumor responses." (PMID 30459443, 2018). "Thus, the use of “young”, less differentiated T cells with longer telomeres, high expression levels of CD27 and CD28 and potent tumor lytic activities is crucial for success." (PMID 28523432, 2017). "A similar trend of increased myeloid cell infiltration was also observed in the spleen when the experiment was repeated in naive non-tumor-bearing mice, indicating that these changes are CD27 related and not tumor driven." (PMID 29198913, 2017). "First, the depletion of CD4+ and CD8+ T cells entirely abrogates anti-CD27 activity, but not combination therapy, signifying that in combination, alternative, synergistic mechanisms of anti-tumor activity come into play." (PMID 29198913, 2017). "The frequency of CD11b+ CD27− mature NK cells was significantly decreased in the spleen of syngeneic HSCT recipients compared with no‐treatment mice, whereas in contrast, it was increased in HSCT tumor." (PMID 26589884, 2016). "Closer analysis revealed that the CD8+/CD27− and CD8+/CD57+ effector T cell fractions strongly increase in NF1 patients with low tumor load and decrease to levels below control in patients with high tumor load." (PMID 27448806, 2016). "The role of CD70-mediated immune escape was also demonstrated in non-small cell lung cancer (NSCLC), where CD27+ lymphocytes were found in the tumor microenvironment with a trend towards increased Foxp3 expression and higher CD4/CD8 ratios surrounding CD70+ tumor cells." (PMID 26605342, 2015). "We have recently demonstrated that incorporation of costimulatory signaling domains, such as CD137 (4-1BB), CD28 or CD27, into a αFR-specific CAR overcomes the limitations of past CAR approaches by improving the persistence and anti-tumor activity of transferred CAR T cells in vivo." (PMID 26101914, 2015).
tumor (continued). "Through its ligand, CD27, the upregulation of CD70 by tumor cells can facilitate evasion of the immune system by three important mechanisms: induction of T cell apoptosis, skewing T cells towards T cell exhaustion, and increasing the amount of suppressive Tregs." (PMID 26605342, 2015). "Furthermore, in this report the expression of CD27, the receptor for CD70, was examined in tumor cells and their microenvironment." (PMID 25951351, 2015). "Among tumor-infiltrating iNKT cells, we found a larger percentage (6%) that expressed markers (CD27 + CD122-) shown to define iNKT2 subset, while only 0.1% had markers of iNKT1 (CD27 + CD122+) cells." (PMID 25349699, 2014). "It is possible that the few immature NK cells (CD27+ CD11b–) in the lungs play a role in limiting pulmonary tumor but are not present in adequate numbers to prevent the tumor completely." (PMID 23776508, 2013). "In addition, as DUC18 CTL mediated tumor regression over days 4–6, the phenotype of effectors within tumors changed dramatically; as expected, CD25 and CD27 expression were markedly down-regulated while mean CD62L expression remained low." (PMID 17786193, 2007). "Further analysis of immune-stimulating factors revealed that in tumors such as LGG, PRAD, and BRCA, the expression of PLAG1 was significantly positively correlated with immune-stimulating factors like CD48, CD27, and TMIGD2, which may enhance anti-tumor immune responses." (PMID 40276502, 2025). "Furthermore, the hCT3 AbTCR group showed a predominance of CD8+ T cells, particularly activated CD8+CD27+ T cells, suggesting that CD8+ hCT3 AbTCR T cells may play a critical role in tumor regression." (PMID 41027430, 2025). "When examining the phenotype of CD27+Ly6C− and CD27+Ly6C+ γδ T cells in KP and KB1P tumor-bearing mice, we found that CD27+Ly6C+ γδ T cells expressed higher levels of CD160, NKG2A, IFNγ, and CD44 in spleen, LN, and lung, analogous to observations made in tumor-naive mice." (PMID 38816652, 2024). "The cluster of differentiation 27 gene (CD27, also known as TNFRSF7) is a member of the tumor necrosis factor receptor superfamily (TNFRSF) and frequently induces both costimulatory and apoptosis-inducing molecules to facilitate anti-tumor and anti-infection immunity." (PMID 38909269, 2024). "Additionally, immune checkpoint molecules (e.g., CCR4, CD27, CD274, CD68, CTLA4, PDCD1, and PDCD1LG2) were significantly upregulated in the AERShigh group (all p < 0.01), suggesting potential impairment of the anti-tumor immune response." (PMID 39464883, 2024). "Finally, TCR usage by KP or KB1P tumor-infiltrating CD27+Ly6C− and CD27+Ly6C+ γδ T cells was the same between subsets with no dominant TCRs emerging within either subset." (PMID 38816652, 2024). "Interestingly, our findings also suggest that CD8 + T cells are not activated as effectively as other CD27-expressing lymphocytes, which significantly inhibit tumor growth and metastasis in a CD27-dependent fashion." (PMID 39105866, 2024). "As MM is a tumor of Ab-producing PCs, precursors of PBs and PCs were identified by increased expression of CD38, decreased expression of CD45, and heterogenous (het) expression of CD19, CD20, CD27, and CD138 with surface membrane Igs (mIgs), such as IgA, IgG, and IgD." (PMID 36752202, 2023). "Therefore, it can be speculated that CD27, PDCD1, TMIGD2 and TNFRSF25 may participate in tumour immunity by regulating IMCPs." (PMID 37849388, 2023). "Differential expression analysis in the tumor compartment between patients with PR versus patients with SD, showed higher PTEN and Ki-67 expression in the former group, while the expression of immune markers, such as Fap-alpha, CD127, CD45RO, and CD27, were found to be decreased." (PMID 37153589, 2023).